SPANXN5 (SPANX family member N5)
Synonyms: SPANX-N5; CT11.10
Tractability: No criterion of Open Targets' tractability assessment is met for any kind of drug.
Gene: Protein-coding gene on chromosome X (52,796,144 to 52,797,427, reverse strand). Ensembl gene ENSG00000204363.
Homologues: Orthologues: chimpanzee SPANXN1 (100% identical). Paralogues in human: SPANXN1 (86% identical), SPANXN2 (71% identical), SPANXN3 (71% identical), SPANXN4 (51% identical).
Diseases named in the same sentence as SPANXN5 in open-access papers:
SPANXN5 is named in the same sentence as 2 diseases in open-access papers, as found by Europe PMC text mining. Sharing a sentence is not in itself a finding about the gene and the disease.
SPANXN5 shares sentences with these, for which no sentence is quoted: metastatic melanoma (1 paper); metastatic tumors (1).